BIN1 (bridging integrator 1)
Diseases named in the same sentence as BIN1 in open-access papers (continued):
Sharing a sentence is not in itself a finding about the gene and the disease.
temporal lobe epilepsy (1 paper, 2020). A localization-related (focal) form of epilepsy characterized by recurrent seizures that arise from foci within the temporal lobe, most commonly from its mesial aspect. "Human genetics also support a link between BIN1 and network hyperexcitability, as the risk allele of the rs744373 variant upstream of BIN1, which is linked to AD, is also associated with impaired memory in temporal lobe epilepsy patients." (PMID 32657270, 2020).
Tetraparesis (1 paper, 2022). Weakness of all four limbs. "Spontaneous canine MTM1 and BIN1 models have previously been reported, and all recapitulated the human disorders at the clinical and histopathological level with severe muscle atrophy, swallowing difficulties and a rapidly progressive tetraparesis." (PMID 35244154, 2022).
tumor (78 papers, 2007 to 2025). "A notable observation was that BIN1 suppresses the prolonged reproductive capacity of aging female mice, while its loss facilitates tumor initiation and progression." (PMID 40346580, 2025). "Beyond its well-established function in preventing malignant transformation, BIN1 has also been implicated in tumor immune evasion and resistance to chemotherapy." (PMID 40346580, 2025). "We observed that BIN1 expression is downregulated in NSCLC tumor tissues, with its reduced expression strongly associated with advanced disease progression and poor prognosis." (PMID 40346580, 2025). "Our prior research revealed that BIN1 regulates the expression of PD-L1 in tumor cells and that its expression is strongly associated with CD8+ T cell infiltration in NSCLC." (PMID 40346580, 2025). "Its role as a tumor suppressor gene suggests a function of wt BIN1 allele as an inhibitor of NF-κB activation." (PMID 35983068, 2022). "BIN1 encodes several isoforms of a nucleocytoplasmic adaptor protein, initially described with tumor suppressor functions." (PMID 35983068, 2022). "Bin1 is a tumor suppressor involved in DNA damage response, and the loss of Bin1 can confer chemotherapeutic resistance." (PMID 35463320, 2022). "The resulting BIN1 isoforms cannot bind to the oncoprotein MYC, causing the BIN1 protein to lack tumor-suppressor activity." (PMID 32760211, 2020). "The BIN1 gene is located on chromosome 2q14.3 and encodes 20 exons, some of which are alternatively spliced, leading to 10 different isoforms and a tumor isoform 11 also termed BIN1 + 12A." (PMID 32164332, 2020). "Here, the authors perform an in vivo shRNA screen in a CEBPA mutant AML mouse model and identify that RBM25 controls the splicing of pre-mRNAs encoding BCL-X and BIN1 to exert its tumour suppressor activities in AML." (PMID 30635567, 2019). "This work focused on the BAR adapter-encoding gene BIN-1, a tumor suppressor previously found to be downregulated in several transformed cell lines and demonstrated to suppress the transformational activity of MYC by interacting with its N-terminus." (PMID 25339948, 2014). "First identified as a tumor suppressor, the bridging integrator 1 (BIN1) has been recently linked to AD susceptibility by GWAS." (PMID 25051234, 2014). "BIN1 is also a potential tumor suppressor implicated in endocytosis and induces membrane tubulation upon overexpression in cultured cells." (PMID 20140253, 2010). "BIN1 was initially identified as a c-Myc interacting pro-apoptotic tumor suppressor; BIN1 expression is reduced in several cancers and mice deficient for BIN1 develop more aggressive tumors." (PMID 21129173, 2010). "Changes in the level of BIN1 isoforms have been linked to tumor progression, which can be induced by modulation of the expression levels of splicing factors." (PMID 17579712, 2007). "Loss of BIN1 tumor suppressor expression is abundant in human cancer and its frequency exceeds that of genetic alterations, suggesting the role of epigenetic regulators (DNA methylation)." (PMID 17477881, 2007). "BIN1 deficiency weakens immune cell function and promotes tumor survival." (PMID 40919170, 2025). "In previous work, it was determined that loss of the BIN1 (bridging integrator 1) tumor suppressor resulted in dysregulated induction of IDO1 in oncogenically transformed skin fibroblasts thereby facilitating immune escape when the cells were grafted into immune competent hosts." (PMID 37182174, 2023). "BIN1 splice variants containing exon 12A abolish the tumor suppressor action of BIN1." (PMID 33801599, 2021). "In addition, the loss of Bin1 expression is associated with various tumor biological characteristics, such as lymph node metastasis and cell apoptosis resistance." (PMID 28152502, 2017).
tumor (continued). "The prevalent isoform of the tumor suppressor BIN1 in cancer, which includes exon 12A, causes the protein to lose its tumor suppressor activity, and the large isoform of tenesin-C (TNC) induces cell migration and was suggested to protect cancer cells from immune surveillance." (PMID 25908786, 2015). "For instance, loss of tumor suppressor genes such as Bin-1 in tumors drives IDO induction via STAT1 and nuclear factor kB, two signaling molecules that have been identified to be key for the inducible IDO expression in myeloid and mesenchymal cells via IFN-g and toll-like receptor (TLR) ligands." (PMID 24657910, 2014). "Bridging Integrator-1 is encoded by the human BIN1 gene and predominantly expressed in the brain and muscle, which is a multifunctional protein that also serves as a tumor suppressor through interacting with Myc; hence, Myc box-dependent-interacting protein is an alias for the BIN1 gene." (PMID 33643380, 2021). "Tumor formation assays demonstrated that tumorigenicity in mice from the BIN1-WT + sh-G3BP1 group was markedly reduced compared to the BIN1-WT group." (PMID 40346580, 2025). "As a tumor suppressor, BIN1 affects tumor proliferation, metastasis, and stemness through the ALDH1/NOTCH2 pathway." (PMID 40016843, 2025). "Our findings demonstrate that BIN1 functions as a tumor suppressor in BLCA and suggest its potential utility as both a diagnostic biomarker and therapeutic target for BLCA treatment." (PMID 40016843, 2025). "IHC analysis of tumor sections from 50 BLCA patients revealed decreased BIN1 expression in higher T-stage BLCA." (PMID 40016843, 2025). "In summary, our findings demonstrate that BIN1 loss-of-function mutations enhance LLC cell proliferation, migration, and invasion, while also promoting tumor growth and reducing apoptosis, both in vitro and in vivo." (PMID 40346580, 2025). "IHC analysis further demonstrated a significant reduction in the positive rates of G3BP1 expression and upregulation in the positive rates of STAT1 expression within tumor tissues in the BIN1-WT + sh-G3BP1 group compared to the BIN1-WT group." (PMID 40346580, 2025). "Reduced or lost BIN1 expression is frequently observed in these malignancies, supporting its role as a tumor suppressor." (PMID 40016843, 2025). "Fluorescence tissue staining revealed a substantial increase in the number of CD8-positive T cells within tumor tissues in the BIN1-WT + sh-G3BP1 group, compared to the BIN1-WT group." (PMID 40346580, 2025). "The results revealed that the tumor growth rate and tumor weight in the BIN1 knockout group were significantly higher compared to those in the control group." (PMID 40346580, 2025). "Through RNA-seq analysis, we demonstrated that BIN1 knockout markedly suppresses STAT1 expression in tumor cells and tissues." (PMID 40346580, 2025). "ELISA analyses revealed that CXCL10 and CCL5 expression levels in tumor tissues were significantly lower in BIN1-KO mice compared to BIN1-WT mice." (PMID 40346580, 2025). "This study highlights the crucial role of the BIN1/G3BP1/STAT1/CD8+ tumor-infiltrating lymphocyte signaling pathway in the progression of NSCLC and its mechanisms of immune evasion." (PMID 40346580, 2025). "In a word, these findings suggest that the STAT1 agonist SB02024 can reverse the immunosuppressive microenvironment induced by BIN1 knockout and enhance anti-tumor immune responses." (PMID 40346580, 2025). "The pro-tumorigenic effects of UBE2O are mediated through its interaction with BIN1 (Bcl-2-interacting protein 1), a tumor suppressor that antagonizes c-Myc transcriptional activity." (PMID 40426910, 2025). "This fundings lay a foundation for the development of BIN1-targeted therapies aimed at improving tumor immunogenicity and transforming immunologically “cold” NSCLC into a more responsive disease." (PMID 40346580, 2025).
tumor (continued). "Intriguingly, the ablation of endogenous BIN1 in tumor cells not only accelerates tumor progression but also diminishes CD8+ T cell infiltration and impairs their functionality." (PMID 40346580, 2025). "This study demonstrates BIN1’s tumor-suppressive role in BLCA, advancing our understanding of this malignancy." (PMID 40016843, 2025). "BIN-1, previously characterized as a tumor-suppressor gene, has been shown to act as a transcriptional repressor of the IDO-1 gene through pathways involving signal transducers as well as activator of transcription 1 (STAT1) and NF-κB." (PMID 39859561, 2025). "Colony formation and tumor sphere formation assays showed inhibited colony and sphere-forming capacities after BIN1 overexpression in UMUC-3 cells." (PMID 40016843, 2025). "BIN1, first identified as a pro-apoptotic tumor suppressor that interacts with and inhibits the oncogenic transcription factor MYC, has complex physiological roles." (PMID 40016843, 2025). "BIN1 has been extensively studied in cancer research and characterized as a tumor suppressor through its interactions with the MYC transcription factor." (PMID 40835006, 2025). "While BIN1 is recognized as a tumor suppressor gene, its role in shaping the tumor microenvironment in NSCLC has yet to be fully clarified." (PMID 40346580, 2025). "Our findings indicate a negative correlation between BIN1 expression and the CSC index, suggesting BIN1’s critical role in modulating tumor cell stemness." (PMID 40016843, 2025). "In all, HIF-1α upregulated circPDK1, which stimulated c-Myc by regulating miR-628-3p/BPTF signaling and lowering BIN1 to enhance glycolysis and tumor progression." (PMID 37208722, 2023). "Bin1+12a isoform was determined to abolish its tumor suppressor role in NSCLC and is promoted by SRSF1 overexpression." (PMID 35463320, 2022). "Altogether, SNHG10 sponges miR-200a-3p to upregulate BIN1 and thereby exerting its tumor-suppressive effects in EOC." (PMID 35149697, 2022). "Taken together, these data provided evidence for the tumor-suppressing role of the SNHG10/miR-200a-3p/BIN1 axis in EOC." (PMID 35149697, 2022). "Recent evidence has demonstrated that BIN1 is a tumor suppressor that interacts with c-myc, thereby limiting c-myc transcriptional activity." (PMID 36068586, 2022). "Among these genes, BIN1 caught our attention due to its tumor-suppressing effect revealed by our previous studies." (PMID 35149697, 2022). "In the literature, BIN1 has been found to inhibit tumor progression in various cancers by suppressing c-myc transcriptional activity." (PMID 36068586, 2022). "The bridging integrator 1 (BIN1) adaptor protein was identified initially as a pro-apoptotic tumor suppressor that binds to and suppresses the oncogenic MYC transcription factor." (PMID 34948122, 2021). "The pro-apoptotic tumor suppressor BIN1 inhibits the activities of the neoplastic transcription factor MYC, poly (ADP-ribose) polymerase-1 (PARP1), and ATM Ser/Thr kinase (ATM) by separate mechanisms." (PMID 34948122, 2021). "This is supported in vivo by the observation that tumor expression of Bin1 is inversely correlated with IDO expression in esophageal squamous cell cancer and lung cancer." (PMID 33072086, 2020). "Bin1 loss in a knockout mouse model was associated with elevated STAT1- and NFκB-dependent expression of IDO, driving tumor immune escape." (PMID 33072086, 2020). "Therefore, impaired BIN1 functions associated with c-Myc oncogenic transformation could be linked to nuclear translocation of cofilin, an actin depolymerizing factor, and result in actin cytoskeleton remodeling and tumor metastasis." (PMID 32164332, 2020). "BIN1 has been identified as a crucial tumor suppressor, which is important in numerous biological behaviors such as proliferation, apoptosis, DNA repair and immune escape." (PMID 31496920, 2019). "Here, we showed that the high expression of CDK5 neutralized the tumor suppressing effect of BIN1 by phosphorylating c-MYC at Ser-62 site." (PMID 31496920, 2019).
tumor (continued). "Bridging integrator 1 (BIN1), also known as Myc box-dependent-interacting protein 1, was identified as a tumor suppressor interacting with MYC box 1, a highly conversed region of the c-MYC N terminus." (PMID 31496920, 2019). "Bridging integrator 1 (BIN1) has showed outstanding tumor-suppressive potential via inhibiting c-MYC-mediated tumorigenesis." (PMID 31496920, 2019). "IDO1 is under genetic control of the cancer-suppression gene bridging integrator 1 (Bin1), and Bin1 knockout results in tumor growth and immune suppression in mice by upregulating STAT1- and NF-κB-dependent expression of IDO1." (PMID 30068361, 2018). "During treatment with cisplatin, one SNV occurred near an intron/extron boundary within BIN1, which is known to interact with the myc oncoprotein as a putative tumor suppressor." (PMID 29208983, 2017). "Bin1, which can function as a tumor suppressor, shows low expression in many malignant carcinomas, including ESCC, but its associated regulation mechanisms, particularly the epigenetic mechanisms, remain elusive." (PMID 28152502, 2017). "BIN1 was initially found as a tumor suppressor with a MYC-interacting domain, a C-terminal SH3 domain, and an N-terminal BAR (Bin1/Amphiphysin/RVS167) domain." (PMID 29056900, 2017). "To identify the effect of DAC on Bin1 methylation in vivo, we injected YES-2 cells harboring fully methylated Bin1 into null mice and detected the tumor volume after 12 days." (PMID 28152502, 2017). "Bridging integrator-1 (Bin1), as a tumor suppressor, is frequently attenuated or even abolished in multiple primary cancers." (PMID 28152502, 2017). "Bin1 is a Myc-interacting adaptor protein with tumor suppressor characteristics, including the suppression of Myc-mediated cell malignant transformation and proliferation." (PMID 28152502, 2017). "For instance, overexpression of SRSF1 in MCF-7 breast cell line has been linked to elevated levels of the isoforms BIN1 +12A and S6K1-p31 which are involved in decreased tumor suppressor activity and increased oncogenic activity, respectively." (PMID 26273588, 2015). "Etoposide can affect transcription also through the bridging integrator-1 (BIN1) protein originally identified as a c-MYC-interacting pro-apoptotic tumor suppressor." (PMID 26600742, 2015). "BIN1 has tumor-suppressor activity by interacting with and activating MYC-mediated apoptosis, except when exon 12A is included by SRSF1-mediated alternative splicing, because the resulting antiapoptotic BIN1+12A isoform is unable to interact with MYC." (PMID 26273603, 2015). "FBLN2, BIN1, FN1 and TNC examples suggest that the variants that are altered in the same direction in several cancer types have significant roles in tumor initiation and progression." (PMID 25908786, 2015). "Studies aimed at understanding how Bin1 restricts tumor outgrowth identified the establishment of immune tolerance through deregulation of IDO1 as a likely explanation." (PMID 26378585, 2015). "A possible answer is emerging from studies of Bin1, a tumor suppressor gene that is often inactivated during cancer, which seems to inhibit cancer development to a significant extent by limiting immune escape." (PMID 26378585, 2015). "For example, BIN1, a nucleocytoplasmic adaptor protein, functions as a tumor suppressor that directly binds and inhibits c-Myc." (PMID 24722255, 2014). "The pathways that we have found to meet these criteria are induced by intrinsic genetic alterations, resulting in the downregulation of both the BIN-1 and TβRIII tumor suppressors and the upregulation of the pro-tumorigenic factors, COX2 and Wnt5a." (PMID 25339948, 2014). "For the elucidation to this phenomenon, e2f-1 can bind directly to promoter of the BIN1 tumor-suppressor gene when DNA is damaged, then trans-activating BIN1 to induce apoptosis." (PMID 24393368, 2014). "The higher methylation proportion of BIN1 showed significant correlation with expressed ER in primary tumor tissue (Spearman's rho test; P < 0.01)." (PMID 22695536, 2012).